SNORD65B (small nucleolar RNA, C/D box 65B)
Gene: Small nucleolar RNA gene on chromosome 8 (41,426,655 to 41,426,727, forward strand). Ensembl gene ENSG00000238936.
Gene Ontology:
Biological process: RNA processing
Cellular component: nucleolus
Homologues: Orthologues: macaque SNORD65B (97% identical), rat LOC120099030 (81% identical). Paralogues in human: SNORD65 (89% identical), SNORD65C (81% identical).